RNU1-56P (RNA, U1 small nuclear 56, pseudogene)
Gene: Small nuclear RNA gene on chromosome X (71,020,275 to 71,020,438, reverse strand). Ensembl gene ENSG00000212605.
Homologues: Orthologues: chimpanzee U1 (99% identical), macaque U1 (96% identical). Paralogues in human: RNU1-1 (87% identical), RNU1-2 (87% identical), RNU1-27P (87% identical), RNU1-28P (87% identical), RNU1-3 (87% identical), RNU1-4 (87% identical), RNVU1-18 (87% identical), RNVU1-29 (87% identical), U1 (87% identical), RNU1-78P (86% identical), RNU1-83P (86% identical), RNVU1-28 (86% identical), and 134 more.